CD4 (CD4 molecule)
Diseases named in the same sentence as CD4 in open-access papers (continued):
Sharing a sentence is not in itself a finding about the gene and the disease.
tumor (continued). "To validate the synergistic effect of IL-21 and PD-L1 on Treg generation in the tumor microenvironment, we used tumor explants freshly isolated from cancer patients to induce Treg generation from CD4+ T cells and to test whether neutralizing IL-21 and PD-1 was capable of blocking Treg generation." (PMID 34026621, 2021). "According to these results, we speculate that T cells that express IL-32 may have a contradictory role that promotes IFNγ expression in CD8+ T cells, which enhances the antitumor activity, and induces CD4+ T cells Foxp3 expression, which suppresses tumor immune response." (PMID 34414188, 2021). "Therefore, we extracted RNA from purified Vb5pos PD1pos and Vb5pos PD1neg CD4 T cells isolated from OT2 Tx recipient mice at tumor endpoint and analogously, from purified Vb5pos PD1pos and Vb5pos PD1neg CD8 T cells isolated from OT1 Tx recipient mice at tumor endpoint." (PMID 34206229, 2021). "Furthermore, IL‐17A expression was found on the majority of CD4+ cells in tumors analyzed, suggesting that CD4+ cells were a dominant source of IL‐17A in the tumor tissues, and implying that IL‐17A‐producing Th subsets might have a potential role on GC." (PMID 34185422, 2021). "Once the APCs have been activated, antigens are presented CD8+ and CD4+ T cells that proliferate and are subsequently recruited back to the treated tumor, as well as, circulate systemically to target and kill distal tumor cells expressing the targeted tumor specific antigens." (PMID 34136405, 2021). "Thus, boosting Th1 and cytotoxic CD4+ T cell responses and inhibiting Tregs functions may obtain optimal anti-tumor responses." (PMID 33791306, 2021). "FABP1 had not been reported to be related to CD4+ T cells, but it could affect the function of tumor-associated macrophages by participating in tumor internal metabolic pathways, and thereby exerting anti-tumor effects." (PMID 34957220, 2021). "CD4 Th1 cells produce interferon-γ (INF-γ), which is an important antiviral cytokine, while CD4 Th2 cells are the source of IL-10, an anti-inflammatory cytokine that suppresses Th1 and NK cells, as well as IL-13, which acts either as a promoter or inhibitor of tumor development." (PMID 34208339, 2021). "Finally, the Tregs in the periphery compromised 9.59 ± 4.30% of the CD4+ T-cells, were characterised by high levels of TIGIT and ICOS expression albeit at lower levels compared to their tumour-associated counterparts (~30% higher median expression, respectively)." (PMID 33917832, 2021). "By analyzing immune cell infiltration in the tumor microenvironment and prognosis, we found that the 5-year OS rate in the group with high CD4+T cell infiltration was lower than that in the group with low CD4+T cell infiltration and was 9.1% and 60.4%, respectively." (PMID 34258299, 2021). "Of note, sample #15A which according to cytology had few intact tumor cells but a high content of mostly degenerative and inflammatory cells including macrophages (which are PD‐L1‐positive) deviated most from the correlation line for multiple markers, for example, CD4, CD5, CD40, and CD83." (PMID 33768639, 2021). "Therefore, low-dose decitabine treated CD4+ T cells had improved anti-tumor activity in vivo." (PMID 33791306, 2021). "As seen from the figure, the composition of tumor-infiltrating immune cells (TIICs) in the high- and low-risk groups remained basically the same, mainly composed of M0 macrophages, CD8 T cells and resting memory CD4 T cells, with significant differences in some immune cells, such as M2 macrophages." (PMID 34170849, 2021). "In addition, compared to auto-CD4+ T cells, AAA-CD4+ T cells produced 4-fold higher amounts of IL-2 transcripts at 24 h post-therapy, which led to more than a 100-fold higher concentration of IL-2 in the local tumor." (PMID 34625113, 2021).
tumor (continued). "However, additional improvement of a multi-epitope vaccine and in relation to the MC-38 tumor model might be achieved by including tumor/MC-38 antigen-specific or bystander CD4+ T-helper cell epitopes in the future." (PMID 34885215, 2021). "Furthermore, despite the molecular mechanism is not fully understood, it has been shown that tumor-derived EVs are able to increase the expansion of CD4+CD25+FoxP3+ Treg cells, inducing their suppressor activity and at the same time blocking the proliferation of activated CD8+ T cells." (PMID 33777750, 2021). "In our analysis, multiple types of immune cells, including CD8+ T cells and CD4+ T cells, were negatively related to the classifier index and down‐expressed in the high‐risk patients, explaining the potential remodeling of tumor immune environment in double‐negative LUAD and LUSC." (PMID 34250747, 2021). "However, regulatory CD4+ cells, such as Th2 and Th17 group, focus on promoting tumor growth." (PMID 34434889, 2021). "In addition, antibody-coated tumor cells could also be processed by dendritic cells, which in turn present tumor antigens to CD4+ T cells and cross-present antigens to CD8+ T cells, aiding in the immune response against tumor cells." (PMID 33494389, 2021). "The tumours from KO mice showed differences in the composition of the immune infiltrate compared with the tumours from WT mice, which included increases in the numbers of TAMs, MDSCs and CD4+ T cells and trends towards decreased numbers of granulocytes and CD8+ T cells." (PMID 33654093, 2021). "In a tumor Ag–specific model, we showed that PD-1 blockade in specific PD-1hiCD39+ CD4 TILs supported proliferation of autologous CD8 T cells specific for the same Ag, implying that CD4 TILs exert helper functions in situ, which could be enhanced by PD-1 blockade." (PMID 33332284, 2021). "Since the microenvironment may be influenced by the genomic composition of tumor, we next investigated whether the CD4 + expression and BioFLIPI were impacted by genetic features of the tumor, as assessed by the validated 23-gene expression profiling panel (23-GEP)." (PMID 34267181, 2021). "Furthermore, during melanoma progression, the expression of CD40L on tumor-infiltrating CD4+ T cells, as well as the expression of interferon (IFN-)γ, tumor necrosis factor (TNF-)α, and IL-2 by these cells, was inhibited, accompanied by increased numbers of Treg and MDSC in the tumor." (PMID 34576054, 2021). "Furthermore, KLRB1 was also expressed by a subset of tumor-infiltrating CD4+ and CD8+ T cells in other tumor types including melanoma, non-small cell lung cancer (NSCLC), hepatocellular carcinoma, and colorectal cancer indicated by several published scRNA-seq datasets 9-12." (PMID 34659549, 2021). "Moreover, PI3Kγ−/− mice with MMTV-PyMT tumors showed increased infiltration of antitumor leukocytes, including B cells and CD4 + and CD8 + T cells, into tumors, and these increased numbers of TILs with loss of PI3Kγ contributed to the diminution of tumor growth." (PMID 33413549, 2021). "However, innate immune response [dendritic cells (DCs), natural killer (NK) cells, TAMs, and tumor-associated neutrophils (TANs)] and adaptive immune response [CD8+ cytotoxic T cells (CTLs), CD4+ T helper 1 (Th1), and B cells] are complementary and interdependent." (PMID 34692696, 2021). "This was quickly followed by a report from the lab of Özlem Türeci and Ugur Sahin, which demonstrated that immunogenic tumour mutations in the ‘mutanomes’ of three separate preclinical mouse tumour models largely induced a CD4+ T cell response, not a CD8+ T-cell response as had been expected." (PMID 32457487, 2021). "In contrast, although the development and effector functions of distinct subsets of CD4+ T cells has been recognised and described, the interplay between polyfunctional CD4+ T cells and other immune cell lineages within the context of tumour immunity is less well understood." (PMID 32457487, 2021).
tumor (continued). "Additionally, as the angiogenesis-related genes such as VEGFs are found to be overexpressed in exhausted CD4+ T cells, our results clearly indicate that CD4+ T cells exhausted by tumor may be involved in neovascularization process of growing tumor." (PMID 34439305, 2021). "Moreover, CD4+ TILs can directly kill tumor cells through cytolytic mechanisms." (PMID 34589578, 2021). "To address the activation status of tumor‐infiltrating T cells, we queried the RNA sequencing data for the expression of a panel of effector and exhaustion markers and observed prominent acquisition of an exhausted T‐cell phenotype in both CD4+ and CD8+ T cells in BrM." (PMID 33755340, 2021). "Our data convincingly show that there is significant inter-patient variability in the GBM tumor ligand expression of various T-cell modulating ligands and consequently striking differences in the methylation pattern and gene expression in tumor infiltrating CD4+ T-cells." (PMID 34012510, 2021). "In addition, it has also been proposed that the milieu of the tumour microenvironment converts effector CD4+ T cells into Tregs or promotes the differentiation of naïve CD4+ T cells into induced Tregs, further exacerbating suppression of nascent anti-tumour immunity." (PMID 32457487, 2021). "In theory, whole tumor cells could be used as a straightforward approach to vaccination and can be administered directly without preloading dendritic cells, generating simultaneous cytotoxic T lymphocytes (CTLs) and CD4+ T cell activation." (PMID 33623783, 2021). "Tumour transcriptome from low immune-ITH showed positive association with cytotoxic NK cells and activated GB+memory CD4+ and PD-1− GB+ CD8+ T cells, or negative association with immunosuppressive Treg, exhausted PD-1+GB−CD8+ T cells and inactive GB− memory CD4+ T cells." (PMID 33431814, 2021). "Furthermore, the flow cytometric analysis of T cells isolated from tumor tissues revealed that the combination of B. longum 420 and following anti-PD-1 antibody treatment significantly increased tumor-infiltrating CD4+ and CD8+ T cells compared to the other treatment groups (p < 0.05)." (PMID 34589578, 2021). "However, the expression of CMTM6 in TCs and ICs was not linked with CD4+ or CD8+ tumor-infiltrating lymphocyte density in either dMMR or pMMR CRC." (PMID 33818637, 2021). "However, CD4 T cells have been shown to exert anti-tumor effects through largely unknown and likely multivalent mechanisms." (PMID 34012443, 2021). "Moreover, treatment with 5ApCB significantly elevated the percentage of CD3+CD4+ T cells, which suggested that the aptamer-decorated bacteria could boost more efficient tumor infiltration of immunologic effector cells." (PMID 34782610, 2021). "Interestingly, another group showed that the accumulation of Salmonella-infected tumor cells undergoing tumor lysis may enable further stimulation of tumor-specific T cell responses, involving both CD4+ and CD8+ T cells, at a later time point post-treatment." (PMID 34829795, 2021). "CD4 Th2 effector cells could be required for establishing long-term anti-tumor memory responses." (PMID 33329566, 2020). "Furthermore, we detected the presence of T-bet+ Tregs (CD3+ CD4+ T-bet+ Foxp3+) only at tumor site." (PMID 32182707, 2020). "Other studies investigated the critical role exerted by T-lymphocytes in containing the malignant clone and in immunosurveillance and hypothesized that the tumor infiltrating CD4+ T cell may be even more important than CD8+ cells in determining patient outcome." (PMID 32731512, 2020). "Interestingly, increased PD-L1 expression in tumor also correlated with higher cytolytic granule components in NK and CD4+ helper T cells from blood, as well as greater frequency of effector memory and lower percentage of naïve CD8+ cytotoxic T cells in the blood." (PMID 33267869, 2020).
tumor (continued). "By using syngeneic tumor models, we confirmed that the combinatory treatment of pemetrexed (without cisplatin) with PD-1/PD-L1 blockage antibodies is sufficient to inhibit tumor growth through the activation and/or recruitment of tumor-infiltrating CD4 and CD8 T-lymphocytes." (PMID 33243934, 2020). "In agreement with this hypothesis, we found that epithelial expression of HLA-DR was highly correlated with stromal expression of CD4 ((Pearson correlation coefficient R2 = 0.67), likely representing recruitment of CD4+ T lymphocytes to the tumor microenvironment." (PMID 32313087, 2020). "Therefore, it was tempting to investigate whether the forced expression of CIITA into tumor cells could render these cells more “visible” and, thus, immunogenic for tumor specific CD4+ Th cells." (PMID 33138029, 2020). "Furthermore, a significant increase in the ratio of GzmB+CD4+Foxp3− to CD4+ Foxp3+ cells was also observed post-treatment, suggesting an inverse relationship between Treg cell frequency and GzmB expression in tumor-infiltrating CD4+ T cells." (PMID 31924474, 2020). "Therefore, to determine the relative and hierarchical involvement of different lymphocyte subsets in tumor control, we compared the growth of Ptgs−/− tumors in Rag1−/− mice or in wild-type mice depleted of either NK cells, CD4+ T cells, CD8+ T cells, or both CD4+ and CD8+ T cells." (PMID 33220234, 2020). "In addition, tumor educated B cells coverts CD4+ T cells to immunosuppressive Tregs." (PMID 33414786, 2020). "Even if cDC2s are in many aspects less efficient than cDC1s, such as in taking up tumor antigens, trafficking to draining lymph nodes, producing IL-12, and stimulating CD8+ T cells, these cells are very efficient in the presentation of MHC-II-associated tumor antigens to CD4+ T cells." (PMID 32486257, 2020). "Factors which might influence the differentiation of Tregs are particularly important in the outcome of tumor immunotherapy, as these cells affect all aspects of anti-tumor response including monocyte/macrophage differentiation, antigen presentation and CD4/CD8 T cell activity." (PMID 32151275, 2020). "Interestingly, there was similar frequency of exhausted CD4 T cells in all tumor types." (PMID 32764562, 2020). "Finally, the percentage of CD4+ or CD8+ T cells in tumor tissues was analyzed by flow cytometry." (PMID 31991820, 2020). "Finally, we wanted to evaluate whether the blockade of TGF-β-signaling in IL-17A+ CD4+ T cells would also impact tumor development." (PMID 32451418, 2020). "Increased expression of genes associated with Cγ chain cytokine signaling and the response to IL-2 in Trp1 Th-ctx is consistent with the cytokine milieu induced by lymphodepletion and could offer mechanistic insights into the acquisition of cytotoxic activity by tumor-reactive CD4+ T cells in vivo." (PMID 31924474, 2020). "Indeed, CD4+ T cells, in the form of T helper cells, could function through monocyte/macrophage system to remove senescent cells and suppress tumor formation." (PMID 33330071, 2020). "However, tumor cells can induce specific immune tolerance in CD4+ T cells." (PMID 32571262, 2020). "Previous study revealed that CD4+ T cells could promote tumor cell proliferation in RCC." (PMID 32662515, 2020). "Our previous studies have shown that the proportion and numbers of CD4+ T cells in peripheral blood and tumor tissues of OC patients were significantly increased, and the high number of CD4+ T cells was positively related to the pathological features and tumor size of OC." (PMID 33102225, 2020). "In a mouse model of epithelial ovarian cancer (EOC) in vitro transfection of CD4+ T cells with miRNA 29a-3p and miR-21-5p mimics, complexed with the commercially available X-tremeGENE siRNA transfection reagent, followed by adoptive transfer into tumor-burdened mice, tumor growth was attenuated." (PMID 32917034, 2020).
tumor (continued). "IHC staining of CD4 in tumor specimens showed that pemetrexed treatment induced a significant increase in the number of CD4+ TILs in tumor areas, suggesting that the tumor cytotoxic effects of pemetrexed may trigger the activation and/or recruitment of CD4+ T helper cells to the tumors." (PMID 33243934, 2020). "In addition, the induction of long-term protective immunity against tumors appears to require concerted recognition of tumor antigens by memory CD4+ and CD8+ T cells, and this may be best achieved by treatment with cancer vaccines plus OV." (PMID 32664210, 2020). "Notably, one study previously reported an association with EMAST and CD8+ but not CD4+ T-cells infiltration in tumour." (PMID 32314040, 2020). "Programmed cell death-1 (PD-1), mostly expressed on effector CD4+ Th cells and CD8+ TILs, binds to its ligands, PD-L1 and PD-L2, on solid tumors, on tumor-infiltrating dendritic cells, and on tumor associated-macrophages and MDSCs, to prevent chronic activation of T cells." (PMID 32823814, 2020). "Indeed, transfer of Blimp-1-deficient CD4+ T cells into tumor-bearing-Rag-1-deficient mice did not control MCA205 tumor growth to the same extent as transfer of WT CD4+ T cells." (PMID 31924474, 2020). "Moreover, B cells memory, T cells CD4 memory resting, T cells CD4 memory activated, T cells gamma delta, T cells regulatory (Tregs), Macrophages M0, Macrophages M1, Dendritic cells activated and Dendritic cells resting were mainly enriched in tumor tissues." (PMID 33043974, 2020). "Moreover, IL‐6 induced CD4+Foxp3+ Treg migration into tumor sites by upregulating CXCR1 expression." (PMID 32931642, 2020). "Future studies should examine whether CSF1/CSF1R acts synergistically with CD4+ Th1 cells to activate anti-tumor CD68+ macrophages, or adaptive CSF1 secretion upon exposure to CD4+ T cell-derived cytokines act detrimentally to recruit M2-like TAMs and consequently hamper antitumor immune responses." (PMID 32850346, 2020). "CD4+ T lymphocytes may inhibit tumor cell growth by cytolysis or by regulating the TME." (PMID 33224872, 2020). "However this activates immune-suppressive CD4+ Treg instead of tumor-destructive CD8+ T cells." (PMID 32887380, 2020). "IL-17A may also enhance tumor growth by suppressing CD4+ and CD8+ T cell infiltration." (PMID 32503584, 2020). "On the one hand, α-melittin-NPs retained the characteristics of melittin that promoted the release of whole-tumor antigens in situ, and we also confirmed that the variety of immunogenic epitopes provided by whole-tumor antigens could activate both CD4+ and CD8+ tumor-specific T cells." (PMID 32111828, 2020). "Thus, we cannot say whether also CD4+ T cells contributed to tumor protection elicited by A/B-based immunization." (PMID 32128342, 2020). "Thus, there is skepticism regarding the anti-tumor effects of CD4+ T cells." (PMID 32226302, 2020). "Besides this, pretreatment of tumor cells with venetoclax could ameliorate the exhaustion status of CD4+ CAR-T cells with reduction of PD-1 expression as well." (PMID 33362794, 2020). "Importantly, we observed the CD8+ Trm T cell formation only in the MAA + Porins immunization and the Porins-alone, which are the groups that could control the tumor growth, this was similar with the CD4+ Trm TILs although its frequency was significantly lower." (PMID 33240271, 2020). "Moreover, there was a significant difference found in absolute CD4 count and tumor stage." (PMID 32118737, 2020). "However, the role of TGF-β for the emergence of IL-17A+IL-22-, IL-17A+IL-22+, and IL-17-IL-22+ CD4+ T cells in the tumor microenvironment remained unknown and was addressed by our study." (PMID 32451418, 2020). "Moreover, CD4 T cells activate innate cells such as macrophages and NK cells to contribute to anti-tumour responses and can also have direct cytotoxic effect against tumour cells expressing MHC class II." (PMID 31915853, 2020).